VDR (vitamin D receptor)
Diseases named in the same sentence as VDR in open-access papers (continued):
Sharing a sentence is not in itself a finding about the gene and the disease.
tumor (455 papers, 1993 to 2026). "The most important reasons for this are thought to be VDR polymorphism, tumor heterogeneity, and downregulation or ablation of VDR during tumor progression." (PMID 40898467, 2025). "The findings also indicate that individuals who carry the CC gene variant tend to have larger tumor sizes and need higher level of VDR expression in order to slow down the progression of the disease." (PMID 40008182, 2025). "Specifically, variants such as FokI and TaqI can alter VDR’s binding affinity to calcitriol, disrupting downstream gene regulation of apoptosis and immune response pathways critical to tumor control." (PMID 40218858, 2025). "For example, in prostate cancer, the VDR ApaI polymorphism was significantly associated with prostate-specific antigen levels and tumor stage, suggesting a role in disease progression and prognosis." (PMID 39683528, 2024). "When correlated with the AJCC anatomic stage/prognostic groups, cytoplasmic expression significantly decreased across the stages, indicating loss of VDR expression with increased tumor progression." (PMID 38265102, 2024). "Subgroup analyses showed that tumour type was the variable affecting the association between VDR expression and OS." (PMID 37561808, 2023). "Scored VDR expression was associated with both favorable patient outcomes and less aggressive tumor characteristics, including smaller tumor size, ER+/PR+, and a lower number of proliferating (Ki67+) cells." (PMID 37835527, 2023). "The role of the vit-D3/VDR axis in the regulation of tumor angiogenesis was linked to the expression of the BRCA1 gene." (PMID 37835527, 2023). "VDR expression in childhood solid tumors has been linked to tumor characteristics and patient survival in only a few studies." (PMID 35884356, 2022). "The VitD3/VDR axis shows regulatory activity in the adaptive immune response, suggesting a possible influence of the nuclear receptor and its polymorphisms on tumor cell growth, inflammation, invasion, metastasis, and angiogenesis." (PMID 36432658, 2022). "More than 60 single nucleotide polymorphisms (SNPs) of VDR gene have been referred to in previous studies as related to carcinogenesis and prognosis at different tumor types." (PMID 36139567, 2022). "Vitamin D3 has been reported to enhance anti‐tumour immunity by increasing the number of tumour associated immunocytes, via tumour VDR suppression of Wnt‐beta catenin signalling." (PMID 35445563, 2022). "Associations between some tumour types and specific single nucleotide polymorphisms (SNPs) within the VDR gene have been investigated." (PMID 35807774, 2022). "When tumor characteristics and VDR status were imputed correctly, this association correlated to an extent that the adjustments for such tumor characteristics diminished the statistical significance." (PMID 36014861, 2022). "Observations of other neoplasms also show that loss of cell differentiation is often associated with reduced VDR expression." (PMID 36362448, 2022). "In particular, VDR positivity was associated with favorable tumor characteristics, as others also have noted." (PMID 36014861, 2022). "It is interesting to note that a modest increase in VDR expression by calcitriol-alone was unable to cause any tumor inhibition effect." (PMID 34199743, 2021). "Furhermore, calcitriol/VDR signalling has the capacity to downregulate cyclooxygenase-2, prostaglandin, and NF-kB pathways, thus inhibiting tumour-associated infammation, to suppress antiapoptotic proteins and to activate pro-apoptotic proteins." (PMID 34034728, 2021). "There is significant association between high VDR tumor expression and good prognostic parameters as low tumor stage (T1) and (N0) nodal stage (P value= 0.02 and 0.01 respectively)." (PMID 33906311, 2021). "There is a direct association between positive VDR expression in tumor cells and positive and high CTLA4 expression in lymphocytes (P= 0.000 and 0.09 respectively)." (PMID 33906311, 2021).
tumor (continued). "There is significant association between high VDR expression in tumor cells and parameters of good prognosis as low tumor stage (T1) and (N0) stage." (PMID 33906311, 2021). "Reduction in VDR expression was also associated with tumor progression, higher mitotic rates, and shorter survival time." (PMID 32429485, 2020). "VDR expression was significantly associated with sex of patients in a way that most male patients exhibited down-regulation of this gene in their tumor tissue samples compared with the paired ANCTs (P = 0.03)." (PMID 32514489, 2020). "In parallel, a deficiency of vitamin D in the diet accelerated the rate of tumor growth, and vitamin D receptor (VDR) ablation further enhanced the tumor volume and metastatic potential." (PMID 32887237, 2020). "The accelerated growth of the tumor and malignancy were contributed to the hyperactive Wnt/β-catenin pathway after the loss of VDR." (PMID 33145139, 2020). "Using the Qiagen database, we predicted that peroxisome proliferator-activated receptor (PPAR) family members, which are closely related to tumor occurrence, were associated with the VDR promoter." (PMID 32900990, 2020). "ECs derived from tumours from Vdr-/- mice showed that vitamin D decreased the proliferation of ECs and loss of VDR lead to an upregulation in the levels of angiogenic factors such as VEGF, HIF-1α, angiopoietin-1 and platelet-derived growth factor." (PMID 31623356, 2019). "According to a report in 2004, clinical tumor stage of PCa would be accelerated by VDR gene polymorphism." (PMID 29467956, 2018). "Numerous mechanisms describing loss of 1,25-D3 responsiveness have been proposed including VDR mutations, differential recruitment of coregulatory proteins, and changes in the epigenetic landscape of tumor cells." (PMID 28811844, 2017). "It has been reported that a higher VDR expression is associated with reduced mortality, favorable tumor characteristics and an improved prognosis in breast, prostate and colon cancer." (PMID 28206978, 2017). "Irrespective of circulating VitD, however, the presence of the tumor was always associated with up-regulation of muscle VDR expression." (PMID 28423519, 2017). "In a large patient population, VDR expression on primary tumor tissue is inversely associated with more aggressive BC including a large tumor size, HR negativity, and triple-negative subtype (p < 0.05)." (PMID 28632174, 2017). "Following orthotopic implantation of MDA-MB-321 cells into the mammary soft tissue, VDR ablation was associated with significantly reduced tumor growth compared to VDR-expressing NT controls." (PMID 28944088, 2017). "Recently, BRCA1 and VDR association has been demonstrated to activated genes involved in anti-tumor effects of vitamin D, and that a complete knockdown of BRCA1 abolishes the effects of vitamin D analogues." (PMID 25992773, 2015). "VDR has been shown to inhibit cell invasion, a hallmark of tumor progression, and yet it has also been reported to be elevated in BCC and SCC." (PMID 25191969, 2014). "Other tumor-associated changes that can lead to 1,25(OH)2D3 resistance in VDR positive tumors include disruption of VDR transcriptional activation and enhanced catabolism of its ligand." (PMID 24982636, 2014). "There was also a significant association identified between VDR-ApaI polymorphisms and tumor differentiation (p = 0.04)." (PMID 23554871, 2013). "A study by Chung and colleagues showed that in tumor-derived endothelial cells from VDR knockout mice, loss of VDR resulted in an increase in HIF-1α, VEGF, angiopoietin 1 and platelet-derived growth factor levels." (PMID 24084056, 2013). "In studies involving patients with colorectal cancer, cholangiocarcinoma, and renal cancer, VDR tumor expression was associated with longer survival." (PMID 23533810, 2013).
tumor (continued). "A number of studies have assessed VDR expression in tumor samples and VDR polymorphisms as prognostic markers." (PMID 23533810, 2013). "There were no other significant associations found between any of the polymorphic VDR variants and tumor stage, tumor differentiation, and ER/PR/HER2 receptor status." (PMID 23554871, 2013). "If the primary effect of VDR loss is to deplete the stem cell compartment VDR −/− mice should be protected from β-catenin induced tumours." (PMID 18213391, 2008). "In summary, we observed associations between SNPs in the VDR gene and BC risk, and a comprehensive analysis using clinical and tumour characteristics as outcome variables has revealed potential associations with MM." (PMID 19105801, 2008). "High tumor VDR expression has also been associated with an upregulation of antitumor immunity." (PMID 41601884, 2026). "The result demonstrated that, in comparison with the VDR-low subset, the VDR-high cases were associated with more aggressive tumor biology, thereby lending credence to the proposition that VDR may function as an oncogene in PCa." (PMID 39963174, 2025). "Loss of VDR expression is well known to promote tumor development and progression." (PMID 41150758, 2025). "Polymorphism in the VDR is known to play a key role in tumor cell metastasis and drug resistance." (PMID 39335182, 2024). "Furthermore, VDR deficiency not only suppressed tumor burden and progression in primary CML mice but also reduced the self-renewal capacity of CML-LSCs." (PMID 37880985, 2024). "Of interest, although it remains unclear what drives the overexpression of VDR, the importance of overexpression of VDR in specific tumor types has been associated with better prognosis and prolonged survival in study participants." (PMID 38318147, 2024). "Also, we found an interaction between a single-nucleotide polymorphism (SNP) of Fok1 (located in the VDR gene) and tumor size in another study conducted by our study group." (PMID 38612962, 2024). "In addition to the VDR, at least two other pathways modify vitamin D signaling and cause tumor growth in VDR null mice." (PMID 38672780, 2024). "Besides the tumor tissue-specific levels of VDR, several non-synonymous and synonymous single-nucleotide polymorphisms (Fok1, Bsml, Apa1, Tru91, and Taq1) in the VDR gene have been found." (PMID 38318147, 2024). "Additionally, VDR can downregulate genes associated with inflammation, thus reducing the pro-inflammatory environment within the tumor microenvironment." (PMID 38230221, 2024). "The involvement of this biomolecule in the expression of tumor genes could be linked to the action of the VDR, since high expression of the VDR gene has been observed in the small intestine and colon." (PMID 37627104, 2023). "At the molecular and cellular levels, we identified the mechanisms by which intestinal epithelial VDR deficiency led to increased gut permeability, disrupted tight junctions, microbial translocation, and enhanced inflammation, thus increasing tumor size and number in the breast." (PMID 37074210, 2023). "At the cellular level, we identified the mechanisms by which intestinal epithelial VDR deficiency led to increased gut permeability, disrupted tight junctions, microbial translocation, and enhanced inflammation, thus increasing tumor size and number in the breast." (PMID 37074210, 2023). "Additionally, recent studies have shown that low VDR protein expression promotes the nuclear deposition of β-catenin in the tumour cells of APC-mutated mice." (PMID 37046222, 2023). "With loss of tumour cell VDR signalling, vitamin D3 signalling in other cells in the TME continues and may gain significance." (PMID 35445563, 2022). "This provides the option of identifying high-risk patients who could benefit from the use of the VDR profile of the tumor as a biomarker and therapeutic alternative (Vitamin D, analogs)." (PMID 35884356, 2022).
tumor (continued). "Thus, sensitivity to growth inhibitory effects of vitamin D3, which would imply effective tumour VDR signalling, was associated with a beneficial effect but a deleterious effect, with immunosuppression, if not." (PMID 35445563, 2022). "Moreover, in tumours with known outcome, histological evidence of low nuclear VDR is associated with progression and metastasis." (PMID 35445563, 2022). "Loss of tumour VDR would leave a direct vascular effect of vitamin D3 unopposed." (PMID 35445563, 2022). "VDR BsmI was found to be significantly associated with tumor stage." (PMID 34199802, 2021). "Notably, other BC subtypes such as ER-positive, PR-positive, and HER2-positive also express VDR in a high percentage of tumor cells, a feature found to be associated with more favorable prognostic characteristics and less aggressive phenotypes." (PMID 34884550, 2021). "Additionally, increased VDR expression was associated with the upregulation of pathways involving the antitumor immune response as demonstrated by a greater abundance of tumor-infiltrating lymphocytes." (PMID 34692525, 2021). "Assessment of association between expression of genes and clinical data showed association between VDR expression and sex of patients in a way that most male patients exhibited down-regulation of this gene in their tumor tissue samples compared with the paired ANCTs." (PMID 32514489, 2020). "When we performed sensitivity analysis for junctional tumours only, there was a greater magnitude of association between VDR expression and overall survival and disease-specific survival, although statistical significance was slightly attenuated for the latter." (PMID 30344947, 2018). "In contrast to Apcmin/+ our results in the Apc1638N/+ model indicate that loss of VDR decreased tumor latency in small and large intestine, increased the occurrence of aberrant crypt foci in the proximal large intestine, but did not affect tumor multiplicity regardless of age." (PMID 27768599, 2016). "Moreover, examination of the AOM-induced tumors revealed that loss of VDR significantly accelerated tumor progression to adenocarcinoma, implying that VDR functions as tumor suppressor during colorectal tumorigenesis in both tumor models." (PMID 27768599, 2016). "A somatic VDR gene mutation could occur, reflecting a mechanism (i.e., loss of tumor-suppressor function) implicated in the malignant transformation of adrenocortical cells." (PMID 26843863, 2015). "This clearly implicates VDR in the control of tumor-associated angiogenesis." (PMID 24084056, 2013). "Association of VDR genotypes with Tumor Pathology and Ethnicity." (PMID 23554871, 2013). "VDR loss may contribute to overactivate the Wnt/β-catenin pathway and so, to accelerate tumor growth and malignization." (PMID 21858154, 2011). "BC and MM tumour pathologies may be influenced by the effect of variation in vitamin D intake through diet and sun exposure, together with VDR polymorphisms." (PMID 19105801, 2008). "However, if VDR signalling promotes the HF lineages, then loss of VDR should change the type of tumour that forms in response to β-catenin." (PMID 18213391, 2008). "However, only a subset of patients responds to this therapy, most probably due to loss of vitamin D receptor (VDR) expression during tumour progression." (PMID 15770204, 2005). "Moreover, CpG methylation level in VDR gene is negatively correlated with CRC risk, indicating that VDR might play tumor-suppressive role in CRC." (PMID 40630116, 2025). "For example, patients with a specific vitamin D receptor variant (VDR FokI T/T), which reduces the biological activity of vitamin D, tend to have faster disease progression and shorter survival regardless of other factors such as age, smoking, or stage of the tumor." (PMID 40282445, 2025). "However, decreased VDR expression in OSCC was associated with tumor relapse, suggesting that vitamin D could be an effective adjuvant chemoprevention agent for residual tumor cells." (PMID 37242229, 2023).
tumor (continued). "Moreover, it also suggests the presence of many confounding factors and genetic roles concerning the VDR polymorphism for this type of tumor, which is still only the subject of study hypotheses." (PMID 37371857, 2023). "Interestingly, the VDR variant genotypes were associated with a decreasing risk of neoplastic disease depending on the presence of the variant allele, and their presence was associated with a significant decreasing trend in OR, particularly for the combined genotypes (ptrend < 0.001)." (PMID 37299554, 2023). "Thus, vitamin D supplementation may suppress the risk of relapse by interacting through VDR expressed in the cells existing within the tumor microenvironment." (PMID 34572935, 2021). "In summary, considering the reported prognostic effect of VDR-rs7299460 and its putative effect on gene transcription, this variant could be speculated to lead to higher VDR expression and improved patient survival by probably affecting the tumor biology and aggressiveness." (PMID 31850208, 2019). "From our results, we don ́t know whether increased VDR expression in oral pre cancerous or OSCCs exhibits a functionally inactivating mutation and this may be due to a feedback loop coupled with an expression by the tumour cells of a defective VDR." (PMID 25662556, 2015). "In this context, it is reasonable to assume that increased cytoplasmic VDR expression in the high-malignant phenotype of OC reflects genetic and/or alterations of regulatory pathways within the tumor microenvironment." (PMID 40332380, 2025). "Further, oncogenic signaling pathways including ERBB2/ERK/AKT, WNT/β-Catenin, JAK/STAT, ERα and NF-κB can reduce VDR levels, thereby reducing the tumor suppressive effect of VD." (PMID 41374952, 2025). "Regarding the VDR genotypes, the expression of VDR among CC carriers was greater because they have larger tumor size that require more VDR expression to prevent from bad prognosis." (PMID 40008182, 2025). "The active form of vitamin D, calcitriol, binds to its nuclear receptor (VDR) and regulates the transcription of numerous genes involved in cell cycle control, differentiation, and tumor suppression." (PMID 41301826, 2025). "The vitamin D signaling pathway plays a critical role in tumor suppression through interactions with its active metabolites, such as 1,25-dihydroxyvitamin D3, which bind to the vitamin D receptor (VDR) and other nuclear receptors like RORα and RORγ." (PMID 40331942, 2025). "In the future, larger series studies including serum vitamin D levels and VDR expression findings in residual tumor tissues after NST are recommended." (PMID 40898467, 2025). "Their influence extends beyond tumor cells to histologically normal adjacent tissue, altering the expression of VDR and E-cadherin in areas surrounding the tumor." (PMID 41301826, 2025). "For instance, in colorectal cancer, VDR expression differs by tumor location and stage, potentially influencing responsiveness to supplementation." (PMID 41377467, 2025). "Vitamin D, particularly its active form 1,25-dihydroxyvitamin D, binds to the vitamin D receptor (VDR) and inhibits tumor cell proliferation while promoting apoptosis." (PMID 40904780, 2025). "This study explored the relationship between VDR expression, patient and tumor characteristics, and patterns of VDR expression dysregulation." (PMID 39963174, 2025). "At the mechanistic level, most evidence supports VD’s role in inhibiting Th17 cell differentiation and IL-17 production via the VDR signaling pathway, thereby mitigating inflammatory responses and suppressing tumor progression." (PMID 40806182, 2025). "Previous studies have shown that chronic inflammation plays a pivotal role in CRC pathogenesis, with VDR‐mediated macrophage polarization acting as a protective mechanism against inflammation‐driven tumor progression." (PMID 40165548, 2025).